RNU7-26P (RNA, U7 small nuclear 26 pseudogene)
Synonyms: U7.26
Gene: Small nuclear RNA gene on chromosome 6 (27,897,504 to 27,897,566, reverse strand). Ensembl gene ENSG00000238610.
Homologues: Orthologues: chimpanzee U7 (100% identical), macaque U7 (95% identical). Paralogues in human: RNU7-8P (89% identical), RNU7-11P (87% identical), RNU7-13P (87% identical), RNU7-27P (87% identical), RNU7-2P (87% identical), RNU7-3P (87% identical), RNU7-4P (87% identical), RNU7-61P (87% identical), RNU7-14P (86% identical), RNU7-23P (86% identical), RNU7-25P (86% identical), RNU7-43P (86% identical), and 142 more.